TMEM61 (transmembrane protein 61)
Tractability: Antibody: UniProt predicts a signal peptide or a membrane-spanning region; the Human Protein Atlas places it where antibodies can reach.
Gene: Protein-coding gene on chromosome 1 (54,886,833 to 54,992,296, forward strand). Ensembl gene ENSG00000143001.
Subcellular location: Membrane
Subcellular location (Human Protein Atlas): Plasma membrane; Vesicles
Gene Ontology:
Molecular function: protein binding
Cellular component: membrane
Genetic constraint (gnomAD): Loss-of-function variants: 13 observed, 12.15 expected, observed/expected ratio (o/e) 1.07, 90% interval 0.69 to 1.67. The upper end of that interval is the gene's LOEUF score, 1.67, which puts it in group 6 of 6, group 1 being the genes least tolerant of losing a copy. Missense variants: 249 observed, 282.8 expected, observed/expected ratio (o/e) 0.88, 90% interval 0.79 to 0.98. Synonymous variants: 109 observed, 124.97 expected, observed/expected ratio (o/e) 0.87, 90% interval 0.75 to 1.02.
Homologues: Orthologues: chimpanzee TMEM61 (99% identical), macaque TMEM61 (91% identical), dog TMEM61 (69% identical), pig TMEM61 (66% identical), rat Tmem61 (50% identical), mouse Tmem61 (47% identical).
Diseases named in the same sentence as TMEM61 in open-access papers:
TMEM61 is named in the same sentence as 1 disease in open-access papers, as found by Europe PMC text mining. Sharing a sentence is not in itself a finding about the gene and the disease. The quoted sentences say what the papers report.
tumor (1 paper, 2023). "In this study, Tmem61 was found to be upregulated at mRNA levels, suggesting its involvement in the synergistic inhibitory effect of tumor growth induced by chitotriose preincubation." (PMID 38248651, 2023).